AGRN (agrin)
Diseases named in the same sentence as AGRN in open-access papers (continued):
Sharing a sentence is not in itself a finding about the gene and the disease.
sarcopenia (continued). "Our findings provide novel evidence of the relevance of AGRN and PRSS12 to sarcopenia phenotypes and support existing physiological data illustrating the importance of the NMJ in maintaining muscle health during ageing." (PMID 36609795, 2023). "We hope our findings encourage future endeavours to further explore the potential role of AGRN and PRSS12 in sarcopenia pathogenesis." (PMID 36609795, 2023). "The single-variant and gene-burden data obtained from UKBB WES data further support the potential relevance of AGRN and PRSS12 to sarcopenia." (PMID 36609795, 2023). "Importantly, if myoblasts become more dependent on neuronal agrin as skeletal muscle ages, increased degradation of neuronal agrin, which occurs in some forms or stages of sarcopenia, could directly contribute to the reduced regenerative capacity of sarcopenic skeletal muscle." (PMID 36233091, 2022). "Sarcopenia and other catabolic conditions disrupt NMJ integrity via proteolytic cleavage of agrin into CAF22 that can be detected in circulation." (PMID 33883602, 2021). "One mouse model of sarcopenia, known as SARCO mice, overexpress neurotrypsin in motor neurons and therefore also have significantly increased agrin cleavage." (PMID 28824419, 2017). "The C-terminal Agrin fragment (CAF) has emerged as a promising biomarker for NMJ degeneration, with higher serum concentrations observed in older adults correlating with decreased muscle strength and sarcopenia." (PMID 41568334, 2025). "Furthermore, elevated plasma levels of a 22 kDa C‐terminal Agrin fragment (CAF), which is cleaved by neurotrypsin, are observed in older adults, and CAF has been proposed to be a potential marker for sarcopenia." (PMID 38461287, 2024). "Nevertheless, it is noteworthy that the effects of AGRN and PRSS12 on sarcopenia phenotypes are likely to be synergistic, whereby changes in PRSS12 expression may stimulate changes in AGRN expression." (PMID 36609795, 2023). "Degradation of Agrin results in structural changes in the NMJ and innervated muscles, consistent with the notion that impaired NMJ functionality plays a role in the onset of sarcopenia." (PMID 37699519, 2023). "Furthermore, although agrin and neurotrypsin are considered to be fundamental for NMJ function, few studies have explored the relevance of AGRN and PRSS12 to sarcopenia." (PMID 36609795, 2023). "A C-terminal, 44 kDa agrin fragment (NT-1654—Neurotune) engineered to be soluble, neurotrypsin resistant and still able to cluster AChRs, has been used with success to treat mice that have undergone disassembly of the NMJ in sarcopenia or nerve injury." (PMID 29462312, 2018). "However, our current investigation reveals a novel aspect by highlighting the contribution of skeletal muscle-derived Agrin, rather than that from motor neurons, in the context of sarcopenia." (PMID 38461287, 2024). "As an overexpression of neurotrypsin-resistant agrin in neurotrypsin knock-out mice could not prevent signs of neuromuscular degeneration at old age, only the subgroup of 30–40% sarcopenia patients with neurotrypsin dependent sarcopenia might be a target." (PMID 24520420, 2014). "While these findings might suggest an increase in Agrin levels in sarcopenia patients, it is crucial to note that the measured CAF represents only a small fragment of Agrin cleaved by neurotrypsin, reflecting the activity of neurotrypsin rather than the overall expression of Agrin." (PMID 38461287, 2024).
congenital myasthenic syndrome (25 papers, 2013 to 2025). Congenital myasthenic syndrome (CMS) is a group of genetic disorders of impaired neuromuscular transmission at the motor endplate characterized by fatigable muscle weakness. "The critical role of the motoneuronal source of agrin is supported by clinical cases of congenital myasthenic syndromes with mutations in the AGRN gene, demonstrating the indispensability of motoneuronal agrin for synapse formation and survival." (PMID 41303670, 2025). "AGRN mutations can induce congenital myasthenia and affect synaptic function and cardiomyocyte regeneration." (PMID 38254942, 2023). "The AGRN gene encodes the protein Agrin, associated with Congenital myasthenic syndrome following an autosomal recessive (AR) pattern of inheritance." (PMID 37035729, 2023). "Pathogenic variants of AGRN compromise AChR clustering and cause congenital myasthenic syndrome (CMS)." (PMID 37108583, 2023). "Firstly, several AGRN variants have been associated with neurological and neuromuscular disorders, including congenital myasthenic syndromes (CMS), a rare group of diseases caused by a severe impairment of synaptic transmission at the NMJ." (PMID 36609795, 2023). "Human cases of congenital myasthenic syndrome caused by AGRN mutations are likely partial loss of function, and complete null alleles are unlikely to survive." (PMID 30953144, 2019). "Human mutations in AGRN cause a congenital myasthenic syndrome that closely resembles phenotype of the mouse point mutation." (PMID 27288508, 2016). "Also referring to other pathologies (congenital myasthenia, distal myopathy) the lack/mutation of agrin has been associated to muscle weakness, atrophy and neurotransmission defects." (PMID 29440993, 2018). "It is worth noting that gene mutations in the agrin-LRP4-MuSK-Dok7-rapsyn-AChR pathway, including the genes AGRN, MUSK, DOK7, RAPSN, cause congenital myasthenic syndromes (CMSs)." (PMID 33328881, 2020). "The variants in FLNC are mainly associated with Hypertrophic cardiomyopathy (not observed in patient 2 or the mother) and variants in AGRN are mainly associated with congenital myasthenic syndrome following an autosomal recessive pattern of inheritance." (PMID 37035729, 2023). "Acetylcholine receptor expression at the motoric end-plates is not noticeably reduced in human agrin deficiency, a rare form of human congenital myasthenic syndrome (CMS)." (PMID 27364156, 2016). "Mutations in Lrp4 that reduce Agrin–Lrp4–MuSK signaling, without perturbing Wnt signaling, cause a neuromuscular disease, termed congenital myasthenia." (PMID 25407677, 2014).
hepatocellular carcinoma (22 papers, 2007 to 2024). A malignant tumor that arises from hepatocytes. "Elevated levels of agrin have been associated with tumor aggressiveness in oral squamous cell carcinoma and hepatocellular carcinoma." (PMID 39334952, 2024). "Among the main heparan sulfate proteoglycans (HSPG), agrin and perlecan are important components of the BM and are over-expressed in some cancers, such as prostate cancer, hepatocellular carcinoma, and breast cancer, and their higher levels associate with tumor development and progression." (PMID 34199373, 2021). "In hepatocellular carcinoma, agrin mediated the Lrp4-Musk signaling pathway and increased the accumulation of cell–ECM adhesions." (PMID 39334952, 2024). "Overall, the HSPG agrin is required for cancer cell response to mechanical stiffness of the ECM in hepatocellular carcinoma cells." (PMID 36693448, 2023). "Agrin is overexpressed and secreted by hepatocellular carcinoma cells, activating the Lrp4/Musk signaling pathway and promoting the assembly of cell-ECM adhesions." (PMID 36693448, 2023). "In hepatocellular carcinoma, agrin acts as a sensor boosting oncogenic signals and regulating Arp2/3-dependent ruffling, invadopodia formation, and EMT through sustained focal adhesion integrity." (PMID 34199373, 2021). "Significant overexpression of AGRN was observed during neoangiogenesis in liver cirrhosis and hepatocellular carcinoma, supporting the notion that AGRN stimulates tumor vascularization." (PMID 29552294, 2018). "Supportively, a recent study also revealed that agrin, MUC16 related gene interact with FAK and agrin-FAK axis drives EMT in hepatocellular carcinoma." (PMID 27382435, 2016). "Agrin is highly expressed in carcinomas such as hepatocellular carcinoma (HCC) and cholangiocarcinoma." (PMID 26558271, 2015). "Here the authors report that Agrin promotes hepatocellular carcinoma by stimulating proliferation, decreasing focal adhesion, increasing invasiveness and promoting an epithelial-to-mesenchymal transition." (PMID 25630468, 2015). "Although originally discovered in the neuromuscular junctions, agrin has been observed in numerous other tissues, and it is described as highly expressed in hepatocellular carcinomas and cholangiocellular carcinomas." (PMID 25506919, 2014). "In hepatocellular carcinoma, it was reported that Agrin senses changes in ECM stiffness." (PMID 38199984, 2024). "AGRN is involved in the proliferation, migration and invasion of liver cancer cells by regulating focal adhesion integrity, and its expression is upregulated in cancers such as hepatocellular carcinoma, promoting EMT in primary tumors." (PMID 36855119, 2023). "Besides, it has also been observed that agrin is overexpressed and secreted in tumor cells such as hepatocellular carcinoma (HCC), and is responsible for enhancing tumor cell proliferation and migration via the Lrp4/MuSK signaling." (PMID 35174224, 2021). "Finally, a recent report from a completely unrelated field of cell biology, the etiology of hepatocellular carcinoma, presents an intriguing possibility for a unified mechanism for synaptogenesis involving integrin, agrin and Lrp4-MuSK signaling." (PMID 31744142, 2019). "Hepatocellular carcinoma exhibits αV integrin and agrin near vessels and bile ducts, suggesting that both molecules may promote cancer progression by increasing angiogenesis." (PMID 26558271, 2015). "Among the main heparan sulfate PGs (HSPG), identified in basement membrane, are agrin and perlecan, which not only were reported to be overexpressed in some cancers, such as prostate cancer, hepatocellular carcinoma and breast cancer, but also had their function associated with tumorigenic events." (PMID 25506919, 2014).
hepatocellular carcinoma (continued). "In the same study, loss of agrin inhibited YAP nuclear translocation on stiff ECM, whereas exogenous addition of agrin induced YAP nuclear translocation, demonstrating the involvement of agrin in mechanically induced ECM stiffness in hepatocellular carcinoma cells." (PMID 39334952, 2024). "AGRN has also been reported as a prognostic marker for HCC70 and promotes the proliferation and migration of hepatocellular carcinoma cells." (PMID 38580754, 2024). "In hepatocellular carcinoma (HCC) cells, AGRN is overexpressed and secreted in high levels compared with non-tumor liver cells." (PMID 36358747, 2022). "Supportively, in a recent study, it has also been shown that a genetically evolved MUC16 related gene agrin has been shown to activate the integrin-FAK pathway and thereby mediate EMT in hepatocellular carcinoma." (PMID 27382435, 2016). "Role of the other basement membrane proteins like agrin, collagen IV, laminin and fibronectin in liver cirrhosis and hepatocellular carcinoma has been studied but no report is available on the functional attributes of Smoc-1 in liver." (PMID 18042303, 2007). "In addition to the accumulation of agrin in the liver of rats undergoing chemically induced cirrhosis and hepatocellular carcinoma (HCC), recent advancements in the field discovered a non-canonical function of agrin as an extracellular matrix sensor that stabilized focal adhesions and promoted HCC." (PMID 29415512, 2018).
liver cancer (14 papers, 2010 to 2025). An epithelial or non-epithelial malignant neoplasm that arises from the liver. "First, sAgrin rescued most of mechanotension deficits and provided pro-migratory benefits to Agrin deficient and proficient keratinocytes in the context of wound healing, as well as in liver cancer cells." (PMID 34732729, 2021). "Indeed, suppression of YAP activity abolished the majority of oncogenic properties associated with agrin overexpression in liver cancer cell lines." (PMID 29415512, 2018). "Second, we tested integrin β1, as it is a well‐known co‐receptor for agrin in liver cancer cells.[13a,e] To this end, we observed minimal interactions between agrin, integrin β1, and EGFR in compliant matrices (0.5 kPa)." (PMID 40165020, 2025). "Together, our study lays the foundation for further evaluation of agrin as a biomarker for improved clinical management of liver cancers." (PMID 39123447, 2024). "Previous studies showed that some proteoglycans, such as glypicans, agrin, and versican, play a key role in the development of liver cancer, and heparan sulfate proteoglycans were regarded to be the critical targets for the diagnosis and therapy of CRC." (PMID 36624500, 2023). "Since liver cancer cells actively stabilize FAs shortly after adherence to fibronectin, agrin ensures that components of the Hippo pathway are primarily excluded from the activated FAs by engaging ILK-PAK1." (PMID 29415512, 2018). "More importantly, combined expression of agrin together with YAP target gene(s) accounted for even poorer survival amongst liver cancer patients." (PMID 29415512, 2018). "Depletion of agrin in liver cancer cells plated on large fibronectin islands shifted YAP into the cytoplasm and reduced the YAP-target gene expression." (PMID 29415512, 2018). "Consistent with its role in liver cancer, soluble agrin also potentiated nuclear YAP localization in cardiac cells, and significantly rescued damage incurred from experimental MI." (PMID 29415512, 2018). "Consistently, recombinant agrin has been reported to induce actin polymerization and fiber formation in the liver cancer cell lines." (PMID 29415512, 2018). "Since agrin is localized to activated integrin clusters in liver cancer cells, this mechanosignalling axis holds a possible key for nullifying the Hippo pathway to promote YAP-dependent tumorigenesis." (PMID 29415512, 2018). "More importantly, pre-treatment of liver cancer cells with arginine-glycine-aspartate (RGD) peptides that block integrin activation also suppressed agrin induced nuclear localization of YAP." (PMID 29415512, 2018). "Furthermore, during HF and liver cancer development, excessive accumulation of agrin, in addition to collagens, laminins, and elastin, will lead to the formation of a stiffer ECM." (PMID 37152902, 2023). "Recently, agrin has been demonstrated to recruit blood vessels within a growing tumor as xenotransplantation of Matrigel plugs containing agrin-depleted human liver cancer cells in immunodeficient mice shows reduced infiltration of murine CD31+ ECs compared to that of the control." (PMID 35174224, 2021). "Moreover, agrin knockdown in liver cancer cells resulted in phosphorylation of YAP (pYAP) at Ser127 and repression of downstream genes." (PMID 33969874, 2021). "Agrin is highly secreted in the circulation of HCC patients, and whether YAP/TAZ through TEAD transcriptional factors enhances agrin expression and secretion in liver cancer will be interesting to examine." (PMID 29415512, 2018). "Understanding the agrin-YAP mechanotransduction loop may help to develop therapeutic strategies against diseases including liver cancer." (PMID 29415512, 2018). "Agrin may thus contribute towards development of motile, invasive actin-rich protrusions known as invadopodia that guide invasiveness of liver cancer cell lines." (PMID 29415512, 2018).
liver cancer (continued). "Accordingly, silencing agrin in the liver cancer cells enhanced YAP Ser381 phosphorylation and de-stabilization of YAP; suggesting that cytoplasmic YAP sequestered by angiomotin and 14-3-3 complexes is likely subjected to proteasomal degradation in response to agrin depletion." (PMID 29415512, 2018). "However, recent shreds of evidence serve the basis for a greater understanding on the role of agrin as a secreted proteoglycan on YAP functions in liver cancer and other tissues." (PMID 29415512, 2018). "Interestingly, agrin may cooperate with Arp2/3 and Cdc42 in the liver cancer cell lines to drive their migratory potential." (PMID 29415512, 2018). "Therefore, it is not surprising to ascertain that agrin tightly maintains the integrity of FA in liver cancer cells which is critical for their underlying oncogenic property." (PMID 29415512, 2018). "Interestingly, upregulation of agrin in primary liver cancers has recently been described." (PMID 20184735, 2010). "A high level of matrix agrin is vital for angiogenesis; this was confirmed by a study in which agrin stimulated angiogenesis by upregulating VEGFR2 levels in liver cancer." (PMID 32825245, 2020). "Clearly, the agrin-induced cellular migratory and invasive capabilities were dependent on YAP activity, as these were significantly reduced in YAP depleted liver cancer cells." (PMID 29415512, 2018). "Here, we discuss the implications of the newly discovered role of agrin and YAP activity in the context of liver cancer, NMJs, and cardiac regeneration." (PMID 29415512, 2018). "Mechanistically, these findings demonstrate that agrin requires YAP-mediated transcriptional activity for its oncogenic property, making it clinically relevant for liver cancer progression." (PMID 29415512, 2018). "Moreover, as YAP activity itself is known to promote ECM stiffness, the fact that supplementation of recombinant agrin exerts considerable stiffness to the local matrix surrounding liver cancer spheroids may be hypothesized as a result of active YAP/TAZ transcription." (PMID 29415512, 2018). "On the clinical perspective, elevated Agrin levels in HCC patient microarray data sets, tumour tissues and circulation of HCC patients cumulatively emphasize a strong role of Agrin in liver cancer." (PMID 25630468, 2015). "Here we reveal the clinical potential of agrin as a key circulatory protein that predicts overall outcomes of liver cancer patients regardless of treatment regimens." (PMID 39123447, 2024). "In this context, at-least in liver cancer cells, depletion of LATS1/2 diminished the enhanced phosphorylation of YAP at Ser127, suggesting the regulation of YAP phosphorylation by agrin may be partially dependent on the Hippo kinases." (PMID 29415512, 2018). "Therefore, the combination of these seminal findings raised a possibility of a mechanotransduction network between agrin and YAP that underscores the oncogenic properties of liver cancer." (PMID 29415512, 2018). "In light of this evidence, the role of agrin in the absence of key Hippo components during the liver cancer development will require extensive future work." (PMID 29415512, 2018). "Moreover, as compliant normal liver tissue matrices do not possess a well-defined basement membrane, excessive accumulation of agrin in addition to fibrillary collagen, laminin and perlecan will lead to the formation of a stiffer ECM during liver cancer development." (PMID 29415512, 2018). "Interestingly, agrin can serve as a mechanotransduction signal, which may transduce ECM and cellular rigidity signals to the Hippo pathway effector YAP, that requires both the Lrp4-MuSK signaling and integrin-focal adhesion signaling in liver cancer cells." (PMID 32208136, 2020).